TNFRSF25 (TNF receptor superfamily member 25)
Description:
Receptor for TNFSF12/APO3L/TWEAK. Interacts directly with the adapter TRADD. Mediates activation of NF-kappa-B and induces apoptosis. May play a role in regulating lymphocyte homeostasis.
Synonyms: LARD; DDR3; DR3; TNFRSF12; TRAMP; WSL-1; WSL-LR; TR3; APO-3
Tractability: Antibody: its Gene Ontology location is reachable by antibodies, with high confidence; UniProt places it where antibodies can reach, with medium confidence; UniProt predicts a signal peptide or a membrane-spanning region; the Human Protein Atlas places it where antibodies can reach.
Gene: Protein-coding gene on chromosome 1 (6,460,786 to 6,466,181, reverse strand). Ensembl gene ENSG00000215788.
Subcellular location: Cell membrane (Isoform 1); Cell membrane (Isoform 2); Cell membrane (Isoform 9); Cell membrane (Isoform 11); Secreted (Isoform 3); Secreted (Isoform 4); Secreted (Isoform 5); Secreted (Isoform 6); Secreted (Isoform 7); Secreted (Isoform 8); Secreted (Isoform 10); Secreted (Isoform 12)
Subcellular location (Human Protein Atlas): Actin filaments; Focal adhesion sites; Plasma membrane; Nucleoplasm; Predicted to be secreted
Pathways (Reactome):
Immune System: TNFs bind their physiological receptors
Gene Ontology:
Molecular function: signaling receptor activity; tumor necrosis factor receptor activity
Biological process: apoptotic process; apoptotic signaling pathway; cell surface receptor signaling pathway; regulation of apoptotic process; signal transduction; tumor necrosis factor-mediated signaling pathway
Cellular component: plasma membrane; cytosol; extracellular region
Genetic constraint (gnomAD): Loss-of-function variants: 29 observed, 47.31 expected, observed/expected ratio (o/e) 0.61, 90% interval 0.46 to 0.84. The upper end of that interval is the gene's LOEUF score, 0.84, which puts it in group 3 of 6, group 1 being the genes least tolerant of losing a copy. Missense variants: 531 observed, 547.9 expected, observed/expected ratio (o/e) 0.97, 90% interval 0.9 to 1.04. Synonymous variants: 240 observed, 223.98 expected, observed/expected ratio (o/e) 1.07, 90% interval 0.96 to 1.19.
Homologues: Orthologues: chimpanzee TNFRSF25 (96% identical), macaque TNFRSF25 (85% identical), rabbit TNFRSF25 (78% identical), pig TNFRSF25 (76% identical), dog TNFRSF25 (76% identical), guinea pig TNFRSF25 (65% identical), mouse Tnfrsf25 (64% identical), rat Tnfrsf25 (60% identical), tropical clawed frog tnfrsf25 (30% identical), zebrafish hdr (13% identical), zebrafish tnfrsfa (13% identical), zebrafish cd40 (12% identical), and 2 more. Paralogues in human: TNFRSF1A (21% identical), TNFRSF10B (15% identical), TNFRSF21 (15% identical), TNFRSF11A (14% identical), TNFRSF10A (14% identical), TNFRSF1B (14% identical), FAS (13% identical), LTBR (13% identical), NGFR (13% identical), TNFRSF8 (13% identical), TNFRSF14 (12% identical), CD40 (12% identical), and 9 more.
Diseases named in the same sentence as TNFRSF25 in open-access papers:
TNFRSF25 is named in the same sentence as 125 diseases in open-access papers, as found by Europe PMC text mining. Sharing a sentence is not in itself a finding about the gene and the disease. The quoted sentences say what the papers report.
autoimmune disease (22 papers, 2010 to 2024). A disorder resulting from loss of function or tissue destruction of an organ or multiple organs, arising from humoral or cellular immune responses of the individual to their own tissue constituents. "TNFRSF25, also known as DR3, plays essential roles in protective inflammation, autoimmune diseases, and tumor immunotherapy." (PMID 34537809, 2021).
inflammatory bowel disease (15 papers, 2013 to 2023). A spectrum of small and large bowel inflammatory diseases of unknown etiology. "Death receptor 3 (DR3; TNFRSF25, TRAMP, LARD, Apo3 and Wsl1) is involved in the pathogenesis of multiple inflammatory conditions such as inflammatory bowel disease, atherosclerosis, allergic lung inflammation and RA." (PMID 28062298, 2017).
colon carcinoma (12 papers, 2011 to 2025). "We found that the immunomodulator TGFBR1 showed positive correlation with TPM1 expression in colon cancer, and the immunomodulator TNFRSF25 showed negative correlation with TPM1." (PMID 34180352, 2021).
lung carcinoma (9 papers, 2008 to 2025). "Tumor necrosis factor receptor superfamily member 25 (TNFRSF25) promoted lymphatic metastasis via VEGF signaling pathway in a mouse model of lung cancer." (PMID 33708105, 2020). "OPCML, TNFRSF25 and TCF21 have been previously reported to be hypermethylated in lung cancer and based on their function, methylation-induced silencing could favor tumor growth." (PMID 18616821, 2008). "Besides, TEDC2 expression was also correlated with TNFRSF25, TNFRSF4 and TNFRSF18 in our analysis, which might be correlated with immune evasion and poor outcome in lung cancer, but the molecular mechanisms of these immune checkpoint molecules still remain elusive and need further investigation." (PMID 36973475, 2023).
atherosclerosis (7 papers, 2013 to 2025). A disease characterized by the build-up of fatty material and calcium deposition in the arterial wall resulting in partial or complete occlusion of the arterial lumen. "In our study, we identified APLNR, PCDH12, PODXL, SLC40A1, TM4SF18, and TNFRSF25 as the most relevant genes associated with lipid metabolism and atherosclerosis, highlighting their potential as diagnostic and immune markers." (PMID 40070840, 2025). "Through further differential analysis and screening using machine learning algorithms, APLNR, PCDH12, PODXL, SLC40A1, TM4SF18, and TNFRSF25 were identified as key diagnostic genes for atherosclerosis." (PMID 40070840, 2025). "Current research has identified TNFRSF25 (the gene encoding DR3) as a critical diagnostic gene for atherosclerosis, highlighting its potential as a novel biomarker for this pathology." (PMID 41268556, 2025). "We determined that APLNR, PCDH12, PODXL, SLC40A1, TM4SF18, and TNFRSF25 are key genes associated with lipid metabolism in samples affected by atherosclerosis." (PMID 40070840, 2025). "Our study employed various machine learning algorithms to identify that APLNR, PCDH12, PODXL, SLC40A1, TM4SF18, and TNFRSF25, among the lipid metabolism genes, can serve as diagnostic markers in patients with atherosclerosis and are associated with atherosclerotic immune infiltration." (PMID 40070840, 2025). "Through our investigation, we discerned the crucial functions of APLNR, PCDH12, PODXL, SLC40A1, TM4SF18, and TNFRSF25 within the framework of atherosclerosis." (PMID 40070840, 2025). "The ROC curve was employed to assess the predictive potential of these key gene markers in atherosclerosis, revealing that the AUC values for APLNR, PCDH12, PODXL, SLC40A1, TM4SF18, and TNFRSF25 were 0.763, 0.859, 0.780, 0.807, 0.792, and 0.848, respectively." (PMID 40070840, 2025).
psoriasis (6 papers, 2015 to 2024). An autoimmune condition characterized by red, well-delineated plaques with silvery scales that are usually on the extensor surfaces and scalp. "As a result, immunostimulatory genes showed higher expression levels within psoriasis than normal tissues, such as CD86, CD48, TNFRSF4, TNFRSF25, ICOS, and CXCR4." (PMID 36685512, 2022).
cervical carcinoma (4 papers, 2015 to 2022). A carcinoma arising from either the exocervical squamous epithelium or the endocervical glandular epithelium. "For immunostimulator, SLC30A10 expression was correlated with TNFRSF25 (Spearman: ρ = 0.202, P = 0.00038), TNFSF13 (Spearman: ρ = -0.193, P = 0.000703), TNFRSF13C (Spearman: ρ = -0.209, P = 0.000245), and RAET1E (Spearman: ρ = 0.197, P = 0.000546) in cervical carcinoma." (PMID 35154468, 2022).
leukemia (4 papers, 2010 to 2025). A malignant (clonal) hematologic disorder, involving hematopoietic stem cells and characterized by the presence of primitive or atypical myeloid or lymphoid cells in the bone marrow and the blood. "Some of these AM genes are known to be dysregulated in leukaemia: up regulation of BIRC3 and down regulation of APAF1, CIDEB, FAS, TNFRSF25, TNFSF10 were previously identified by our group as specific alterations of AM genes in leukemic cells." (PMID 20642818, 2010).
viral infection (4 papers, 2017 to 2023). "Activation of TNFRSF25 by its ligand, TNFSF15, is important for T‐cell proliferation during viral infection control as it enhances interferon‐g (IFN‐g) synthesis." (PMID 36039012, 2023).
glioma (3 papers, 2021 to 2024). A benign or malignant brain and spinal cord tumor that arises from glial cells (astrocytes, oligodendrocytes, ependymal cells). "Furthermore, we found that 5 immune inhibitors (KDR, TIGIT, VTCN1, LAG3 and ADORA2A) and 2 immune stimulators (ICOS and TNFRSF25) were significantly associated with HIC2 in gliomas." (PMID 36650953, 2023). "In glioma cells, it was observed that the expression of genes related to MRM, like GTPBP3, METTL2A, METTL6, METTL8, NSUN4, and TRMT61A, showed positive correlation with the expression of HAVCR2, PVR, TNFRSF25 and TNFSF15 as revealed by scRNA-seq analysis." (PMID 38824202, 2024). "The expression of HAVCR2, PVR, TNFRSF25, and TNFSF15 showed a positive correlation with the expression of numerous MRM-related genes like GTPBP3, METTL2A, METTL6, METTL8, NSUN4, and TRMT61A in glioma cells." (PMID 38824202, 2024).
multiple sclerosis (3 papers, 2014 to 2023). A progressive autoimmune disorder affecting the central nervous system resulting in demyelination. "Finally, astrocyte cluster 8 (MMP7, SERPINA3, GZMA, and CLIC1) and microglial cluster 2 (DSG2 and TNFRSF25) were elevated in multiple sclerosis patients and suggested the pathogenic role of these biomarkers during multiple sclerosis progression." (PMID 37468977, 2023).
Sepsis (3 papers, 2023 to 2025). Sepsis is defined as life-threatening organ dysfunction caused by a dysregulated host response to infection. "Downregulated genes in sepsis Th2 cells were significantly overrepresented in processes related to viral responses (including TNFRSF25 and GIMAP5; -0.79 and -0.49log2FC, respectively) and differentiation (ZAP70; -0.66log2FC)." (PMID 41208955, 2025).
Anxiety (2 papers, 2021 to 2025). Intense feelings of nervousness, tension, or panic often arise in response to interpersonal stresses. "Interestingly, among the anxiety- and depression-related DEGs, we found the upregulation of Bcl3, C3, Gpat3, and Tnf in the AMY as well as the increased expression of Crhr2, Nant, Sar1a, and Tgif1 and the decreased expression of Ier2, Il12a, Nrep, and Tnfrsf25 in the ACC." (PMID 33898422, 2021).
bladder cancer (2 papers, 2008 to 2013). "Tumor necrosis factor receptor superfamily member 25 (TNFRSF25) has been shown to be methylated in bladder cancer, and very recently methylation in lung SQ was reported." (PMID 18616821, 2008).
COVID-19 (2 papers, 2024). A disease caused by infection with severe acute respiratory syndrome coronavirus 2. "ILCp cells from COVID-19 patients showed upregulated expression of IL2RA (adj.p = 0.004), IL4R (adj.p = 2.3e-11) as well as other immune-related genes including TNFRSF25 (adj.p = 4.2e-03) and CCR7 (adj." (PMID 39026668, 2024).
endothelial dysfunction (2 papers, 2021 to 2025). In vascular diseases, endothelial dysfunction is a systemic pathological state of the endothelium (the inner lining of blood vessels) and can be broadly defined as an imbalance between vasodilating and vasoconstricting substances produced by (or acting on) the endothelium. "WGCNA prioritized the MEbrown module, enriched in inflammation-related genes (e.g., TNFRSF25, CASP5), which aligns with prior work linking TNF receptor superfamily members to endothelial dysfunction." (PMID 40826682, 2025).
hearing loss (2 papers, 2025 to 2026). "Our data show a higher level of methylation in the ESPN and TNFRSF25 CpG sites in patients with severe hearing loss at 8 KZ compared to the patients with mild and moderate hearing loss." (PMID 40428348, 2025).
osteosarcoma (2 papers, 2015 to 2023). A usually aggressive malignant bone-forming mesenchymal neoplasm, predominantly affecting adolescents and young adults. "In addition, DIO3OS may be a novel immunotherapeutic target for osteosarcoma by suppressing immune checkpoints (CD200 and TNFRSF25) and is a novel diagnostic biomarker to distinguish osteosarcoma from multiple other subtypes of sarcoma." (PMID 37752544, 2023). "Therefore, silencing DIO3OS expression may improve the efficacy of osteosarcoma immunotherapy by inhibiting immune checkpoints (CD200 and TNFRSF25)." (PMID 37752544, 2023). "Therefore, knockout DIO3OS may be a novel immunotherapy for patients with osteosarcoma by inhibiting immune checkpoints (CD200 and TNFRSF25)." (PMID 37752544, 2023).
adenoma (1 paper, 2015). A neoplasm arising from the epithelium. "However, of the Ip-adenomas, 10 (45 %) were TNFRSF25 positive." (PMID 26048755, 2015). "Immunohistochemical staining showed that BCL2L1 and TNFRSF25 proteins were significantly up-regulated in LST-adenoma, compared to Ip-adenoma (p = 0.010, p < 0.001)." (PMID 26048755, 2015). "By K-means clustering, the expression levels of five genes, AKT1, BCL2L1, ERBB2, MTA2 and TNFRSF25, were seen to be significantly up-regulated (p <0.05) in LST-adenoma compared to Ip-adenoma." (PMID 26048755, 2015). "According to our IHC analysis, TNFRSF25 protein was also up-regulated in LST-adenoma, compared to Ip-adenoma (p < 0.001)." (PMID 26048755, 2015). "As a result of K-means clustering, the expression levels of five genes, AKT1, BCL2L1, ERBB2, MTA2 and TNFRSF25, were found to be significantly up-regulated (p < 0.05) in LST-adenoma, compared to Ip-adenoma." (PMID 26048755, 2015). "Of the LST-adenomas, 25 (66 %) were BCL2L1 positive and 38 (100 %) were TNFRSF25 positive." (PMID 26048755, 2015).
Lymphatic Metastasis (1 paper, 2021). Transfer of a neoplasm from its primary site to lymph nodes or to distant parts of the body by way of the lymphatic system. "The expression levels of RELT, TNFSF18, and TNFRSF25 were high, and the expression levels of EDA2R were low in patients with lymphatic metastasis." (PMID 34484286, 2021).
oral cancer (1 paper, 2022). "All above findings indicated the different roles of TNFRSF25 and TNFRSF12A in p-EMT tumor cells in non- vs. metastasis conditions of oral cancer, and TNFRSF12A is highly associated with tumor cell metastasis transcription factor SNAI2." (PMID 35742914, 2022).
skin inflammation (1 paper, 2019). "Hh also reduced expression of other genes for inflammatory signaling pathways implicated in skin inflammation including TNFR (Tnfrsf25), JAK-STAT (Jak1), and NF-κB (Trl4, Myd88, Cd69, Cd48, Irf1)." (PMID 31264977, 2019).
thyroid cancer (1 paper, 2022). "Using the TISIDB database, we demonstrated that ALDH1A1/A3/B1 had significant negative correlations with immune-stimulating genes, such as CD276, TMEM173, TNFSF9, CD70, TNFRSF25, and CD40 in thyroid cancer." (PMID 35280765, 2022).
cancer (51 papers, 2010 to 2025). A tumor composed of atypical neoplastic, often pleomorphic cells that invade other tissues. "The expression profiles of cancer-related checkpoints showed that the majority of checkpoint-target genes had low expression levels in the high-risk group, and only TNFRSF25, TNFRSF4, TNFRSF14, TNFRSF18, and CD276 were upregulated in the high-risk group." (PMID 37190215, 2023). "Tumor necrosis factor receptor superfamily 25 (TNFRSF25) is a T cell co stimulatory receptor and a potential target for cancer therapy." (PMID 41001045, 2025). "It dampens the suppressive capacity of Treg cells, implying that an agonistic antibody for TNFRSF25 is an attractive agent for cancer immunotherapy." (PMID 36039012, 2023). "Among the immunostimulatory factors, IL6R, TNFRSF18, TNFRSF25, and ULBP1 were significantly associated with RCC2 expression in the majority of cancer types." (PMID 36441563, 2022). "BGLAP expression was positively and significantly correlated to TNFRSF25 in all these cancer types except CESC." (PMID 33240930, 2020). "The most significantly up-regulated genes included TNFRSF25 (+3.4) and ITGB3 (+6.96), which have been shown to induce apoptosis, and have been associated with increased survival in cancer." (PMID 27586635, 2016). "Similarly, ZNF668 was positively correlated with PVRL2 (Nectin-2), CD276 (B7-H3), TGFB1, and multiple members of the TNF receptor superfamily, including TNFRSF4 (OX40), TNFRSF18 (GITR), and TNFRSF25, in the vast majority of analyzed cancers." (PMID 41614761, 2025). "Interestingly, RELL2 expression in tumors was associated with the expression of several checkpoint inhibitors in several cancers including TNFRSF25 (DR3)." (PMID 37893069, 2023). "However, the association of CD36 expression with CD274 (PDL-1), TIGIT, and TNFRSF25 was cancer type-specific." (PMID 34234847, 2021). "The function of TNFRSF25 in cancer development and progression remains unclear." (PMID 36002754, 2023). "Two immunomodulators, TNFSF14 and TNFRSF25, were found to regulate GSDMB gene expression in cancers." (PMID 37064151, 2023). "The immune checkpoint genes TNFRSF25 and ADORA2A were positively correlated with METTL3 expression in most cancer types." (PMID 36614956, 2022). "According to the correlation analysis between SRSF3 and immune checkpoint gene expression, it can be found that SRSF3 is closely related to TNFSF14, TNFRSF14, TNFRSF25, CD276, NRP1, VSIR in a variety of malignant tumors (P <0.05)." (PMID 35494088, 2022). "In diverse cancer types, the correlation between OAS3 and the expression of checkpoint genes indicated a high correlation with TNF-related immune genes including TNFRSF14, TNFRSF8, TNFRSF25, TNFRSF4, TNFRSF18, TNFSF15, and TNFRSF9." (PMID 35592250, 2022). "Additionally, CSNK1D showed a positive correlation with TNFRSF25 and CD276 in most cancers." (PMID 37688771, 2023). "Among these immunostimulators, TNFRSF25 and TNFRSF14 showed a negative coexpression in more than 10 cancers." (PMID 38655053, 2024).